RNU6-337P (RNA, U6 small nuclear 337, pseudogene)
Gene: Small nuclear RNA gene on chromosome 7 (79,030,240 to 79,030,345, forward strand). Ensembl gene ENSG00000212545.
Homologues: Orthologues: chimpanzee U6 (98% identical), macaque U6 (94% identical), guinea pig U6 (78% identical), rabbit U6 (77% identical), pig U6 (76% identical), mouse Gm24378 (74% identical), rat LOC120097314 (72% identical). Paralogues in human: RNU6-1209P (85% identical), RNU6-445P (84% identical), RNU6-15P (83% identical), RNU6-183P (83% identical), RNU6-188P (83% identical), RNU6-524P (83% identical), RNU6-686P (83% identical), RNU6-1287P (82% identical), RNU6-21P (82% identical), RNU6-26P (82% identical), RNU6-345P (82% identical), RNU6-371P (82% identical), and 1287 more.